AIM2 (absent in melanoma 2)
Diseases named in the same sentence as AIM2 in open-access papers (continued):
Sharing a sentence is not in itself a finding about the gene and the disease.
type 2 diabetes (16 papers, 2019 to 2025). "It has been shown that AIM2 inflammasomes directly interact with apoptosis-associated speck-like protein and contribute to the development of many human diseases, including type 2 diabetes, where cell-free mtDNA has been shown to activate AIM2 inflammasomes." (PMID 36429063, 2022). "Our results suggest that ccf-mtDNA-dependent AIM2 inflammasome activation is associated with chronic inflammation in patients with type 2 diabetes." (PMID 30965677, 2019). "Interestingly, a significant positive correlation existed between clinical periodontal parameters in type 2 diabetic patients, such as the gingival index, clinical attachment loss, periodontal inflamed surface area and salivary levels of AIM2, IFI16, and IL18." (PMID 41440367, 2025). "In patients with type 2 diabetes, increased mtDNA levels were associated with IL-1beta levels and may contribute to chronic melanoma 2 (AIM2) inflammasome mediated inflammation." (PMID 34211456, 2021). "Increased levels of AIM2 and circulating mitochondrial DNA, as well as various cytokines, were observed in type 2 diabetes." (PMID 38673935, 2024). "Mitochondrial DNA from patients with type 2 diabetes mellitus can trigger AIM2 inflammasome-dependent caspase-1 activation, leading to the release of proinflammatory cytokines and promoting polarization to the M1 phenotype." (PMID 38673935, 2024). "Circulating cell-free mitochondrial DNA derived from type 2 diabetes patients is able to activate the AIM2 inflammasome in macrophages, suggesting a role for the AIM2 inflammasome in the induction of chronic inflammation during type 2 diabetes." (PMID 32630319, 2020). "We analyzed caspase-1 activation and the IL-1β and IL-18 secretion in lipopolysaccharide (LPS)-primed bone marrow-derived macrophages (BMDMs) stimulated with ccf-DNA from patients with type 2 diabetes and poly(dA:dT), an AIM2 inflammasome activator." (PMID 30965677, 2019). "Although the role of NLRP3 inflammasome activation has been demonstrated, the activation of AIM2 inflammasome during type 2 diabetes is not well known." (PMID 30965677, 2019). "In this study, we demonstrate that elevated ccf-mtDNA levels contribute to chronic inflammation via AIM2 inflammasome activation in patients with type 2 diabetes." (PMID 30965677, 2019). "In this study, we demonstrate that ccf-mtDNA contributes to AIM2 inflammasome-mediated chronic inflammation in patients with type 2 diabetes." (PMID 30965677, 2019). "The mtDNA, from patients with type 2 diabetes, induced absent in melanoma 2 (AIM2) inflammasome-dependent caspase-1 activation and IL-1β and IL-18 secretion in macrophages." (PMID 30965677, 2019). "Our results, taken together, suggest that the ccf-mtDNA-mediated AIM2 inflammasome activation provides a mechanism for chronic inflammation in type 2 diabetes." (PMID 30965677, 2019). "The mtDNA from patients with type 2 diabetes induced AIM2 inflammasome-dependent caspase-1 activation, and IL-1β and IL-18 secretion in macrophages." (PMID 30965677, 2019). "In addition to the role of NLRP3, AIM2 has been suggested to play a role in the pathogenesis of type 2 diabetes (T2D) as its expression levels were reported to be upregulated in patients with T2D compared to healthy controls." (PMID 41440367, 2025). "In patients with type 2 diabetes, activation of the AIM2 inflammasome induced chronic inflammation." (PMID 34861878, 2021). "In addition, there is accumulating evidence for AIM2 to be involved in sustaining mitochondrial function by detecting mitochondrial DNA (mtDNA) in various human diseases, including cancer and diabetes type 2, as well as in detecting virus-induced oxidized DNA." (PMID 32933486, 2020). "Furthermore, the mtDNA from patients with type 2 diabetes increased AIM2 inflammasome activation in macrophages." (PMID 30965677, 2019).
type 2 diabetes (continued). "Our findings suggest that the ccf-mtDNA may act as a critical signaling molecule in chronic inflammation via AIM2 inflammasome activation in metabolic diseases, including type 2 diabetes." (PMID 30965677, 2019). "Our results suggest that the ccf-mtDNA might contribute to AIM2 inflammasome-mediated chronic inflammation in type 2 diabetes." (PMID 30965677, 2019). "Currently, the role of ccf-mtDNA in AIM2 inflammasome activation-dependent chronic inflammation during type 2 diabetes remains unclear." (PMID 30965677, 2019). "Moreover, evidence suggests that development of type 2 diabetes mellitus may be supported by reduced total methylation of AIM2 promoter region." (PMID 36072791, 2022). "To investigate a molecular target of ccf-mtDNA in regulating chronic inflammation in type 2 diabetes, we examined ccf-DNA, which has high mtDNA levels, from patients with type 2 diabetes to determine whether it could induce AIM2 inflammasome activation in macrophages." (PMID 30965677, 2019).
Cognitive impairment (15 papers, 2020 to 2025). Abnormal cognition is characterized by deficits in thinking, reasoning, or remembering. "AIM2 inflammasome was found to promote long-term cognitive impairment and memory loss induced by chronic cerebral hypoperfusion." (PMID 35722622, 2022). "The genetic deficiency of AIM2 can attenuate inflammasome-mediated proinflammatory cytokine release, apoptosis and cognitive impairment following BCAS." (PMID 36012981, 2022). "In a mouse model of MCAO/reperfusion-induced post-stroke cognitive impairment, AIM2 expression was significantly elevated in the hippocampus and cortex relative to controls." (PMID 35722622, 2022). "The deletion of AIM2 in microglia has been demonstrated to improve cognitive impairment and synaptic deficits in an Aβ1-42-induced AD mouse model, suggesting the activation of microglia-mediated by AIM2 contributes to the inflammasome-mediated neuroinflammatory processes seen in AD." (PMID 40427569, 2025). "Genetic deletion of AIM2 attenuated cognitive deficits in AD and VaD models." (PMID 40521199, 2025). "In addition, AIM2 inflammasome contributes to neuroinflammation and cognitive impairment in MCAO mice." (PMID 40717974, 2025). "Furthermore, activation of the AIM2 inflammasome substantially contributes to the pathophysiology of chronic cerebral hypoperfusion‐induced brain injury and related cognitive impairment." (PMID 37177836, 2023). "Furthermore, in a VaD model with AIM2 inflammasome overexpression, M2exo@HMPB inhibited the activation of AIM2 inflammasomes and cell pyroptosis in microglia, thereby alleviating chronic cerebral hypoperfusion-induced neuronal cell death and cognitive impairment." (PMID 40521199, 2025). "Unexpectedly, Aim2 deletion in 5xFAD mice attenuates Aβ load and microglia activation but does not improve the cognitive impairment and secretion of IL-1β and IL-18, while Aim2 deletion in APP/PS1 mice rescues all of them." (PMID 38467840, 2024).
glioma (15 papers, 2012 to 2025). A benign or malignant brain and spinal cord tumor that arises from glial cells (astrocytes, oligodendrocytes, ependymal cells). "Most of these genes are risk factors for glioma, but NLRP1 and AIM2 have favorable effects on prognosis of glioma." (PMID 37501725, 2023). "As previously reported, the anti-tumor role of AIM2 has been reported in brain cancer, including gliomas." (PMID 40002808, 2025). "By using the public TCGA database, it was found that AIM2 was highly expressed in G2, G3, and G4 gliomas and was frequently altered in low grade gliomas." (PMID 40002808, 2025). "Although there have been considerable studies on the pathological function and mechanism of the AIM2 inflammasome in other tumors, reports in gliomas have been relatively unclear." (PMID 37723542, 2023). "AIM2 is extensively expressed in G2, G3, and G4 gliomas in TCGA database, networks with each inflammasome receptor, and epigenetic alteration patterns." (PMID 37723542, 2023). "Another controversial function of AIM2 inflammasome in glioma was hinted at in the late phase of experimental autoimmune encephalomyelitis (EAE) and a mouse model of multiple sclerosis." (PMID 37723542, 2023). "From functional aspects, inhibition of the AIM2 inflammasome increases the proliferation of gliomas and increases temozolomide resistance in vitro, a somewhat controversial function compared to its function in other diseases." (PMID 37723542, 2023). "We used a data-driven approach to identify NLRs, AIM2 and NLR-associated gene expression and methylation patterns in low grade glioma and glioblastoma, using The Cancer Genome Atlas (TCGA) patient datasets." (PMID 31186453, 2019). "In the present study, we have generated an extended network using seed genes (NLRs and AIM2) in glioma." (PMID 31186453, 2019). "Many of these up-regulated TAPPs are common in gliomas and other brain cancers, such as Aim2, EZH2, GP100, Mage-1, MageA4, MageA10, Sart-1, -3, Trp-1, and Sox2." (PMID 26175925, 2015). "Hypoxic glioma cell lines increased their mRNA expression for nine TAPP (Aim2, Art-4, EphA2, EZH2, Fosl1, PTH-rP, Sox 11, Whsc2 and YKL-40), as assessed by quantitative reverse transcriptase real-time/polymerase chain reaction (qRT-PCR)." (PMID 22957023, 2012). "Nine TAPPs from the glioma cells (Aim2, Art-4, EphA2, EZH2, Fosl1, PTH-rP, Sox11, Whsc2 and YKL-40) consistently exhibited increased mRNA presence (≥1.9-fold expression) after culturing the cells in hypoxia (1% O2)." (PMID 22957023, 2012). "Moreover, the experimental data obtained by using multiple cell lines demonstrated that ASC and AIM2 protein expression was higher in lipopolysaccharide (LPS)-primed LN18 glioma and BV2 microglial cells compared to the control." (PMID 40002808, 2025). "Notably, since 2019, the existence and function of the AIM2 inflammasome in glioma has been elucidated." (PMID 37723542, 2023). "There is a dearth of reports linking NLRs and AIM2 to glioma pathology." (PMID 31186453, 2019). "Many of the TAPP were not differentially expressed in the hypoxic cells but nine TAPPs from the glioma cells (Aim2, Art-4, EphA2, EZH2, Fosl1, PTH-rP, Sox11, Whsc2 and YKL-40) consistently exhibited increased mRNA presence after culturing the cells in response to hypoxia." (PMID 22957023, 2012). "Quantitative RT-PCR showed that cellular DNA sensors STING, AIM2 and cGAS were not consistently up-regulated in the two stocks of human primary glioma cells upon ADV infection." (PMID 32843056, 2020). "Therefore, we looked at the expression of differentially expressed genes, ASC/PYCARD, AIM2, and CASP1 under normal and inflammatory conditions in microglia and glioma cells." (PMID 31186453, 2019). "However, this research did not rule out the anti- or pro-carcinogenic activity of AIM2 in the establishment and progression of gliomas and glioblastomas." (PMID 40002808, 2025).
glioma (continued). "Indeed, in patient-derived glioma stem cell lines and established human glioma lines, TTF treatment induced formation of cytosolic micronuclei clusters and activation of type I IFNs in an AIM2- and STING-dependent manner." (PMID 38226619, 2024). "Additionally, DNA methylation analysis demonstrated that the promoter methylation levels of AIM2, CASP1, CASP8, NLRP3, and ZBP1 are significantly lower in gliomas than in non-tumor brain tissues." (PMID 39901195, 2025).
prostate carcinoma (15 papers, 2016 to 2025). A carcinoma that arises from epithelial cells of the prostate gland. "Elevated expression level of AIM2 in senescent prostate epithelial cells is associated with increased IL-1β production and development of benign prostatic hyperplasia, whereas the expression of AIM2 in prostate cancer cells is low." (PMID 28526809, 2017). "According to these pieces of evidence, it is possible to conclude that the AIM2 inflammasome has a pro-tumor function in prostate cancer." (PMID 40002808, 2025). "Recent studies showed that AIM2 inflammasome plays a critial roles in the tumor progression of prostate cancer." (PMID 29423077, 2018). "Using Gene Expression Omnibus (GEO) public datasets, we screened the expression profiles of inflammasome sensors NLRP3, NLRC4, NLRP6, NRLP12, and AIM2 in prostate tumor tissues, and verified their mRNA level in a panel of prostate cancer cell lines." (PMID 28663562, 2017). "Further, hypoxia potentiated activation of the NLRP3 and AIM2 inflammasome in prostate epithelial, prostate cancer, and THP-1 cell lines." (PMID 27058421, 2016). "IFNs treated prostate cancer cell lines showed increased AIM2 activating inflammasome complex leading to production of IL-1β and IL-18." (PMID 27429614, 2016). "Moreover, the cytoplasmic DNA (derived from pathogens, necrotic cells, or senescent cell-derived exosomes) existing in normal primary human prostate epithelial cells (PrECs) and prostate cancer (PC-3 cell line) can activate the AIM2 inflammasome." (PMID 36702978, 2023). "This suggests that the expression patterns of Caspase-1 and the AIM2 inflammasome might have prognostic significance for disease progression in prostate cancer." (PMID 36702978, 2023). "Activation of AIM2 was served as a biomarker to identify the molecular mechanisms through prostatic infections and/or sterile inflammation contribute to the carcinogenesis of prostatic cancer." (PMID 29423077, 2018). "It is likely that additional factors are required to activate and organize the formulation of NLRP12 inflammasome complex, similar to activation of AIM2 by the interferons (IFNs) in prostate cancer cell lines activating AIM2 inflammasome leading to interleukins IL-1β and IL-18 production." (PMID 28663562, 2017). "Because hypoxia in prostatic tumors is associated with chronic inflammation and a poor outcome for prostate cancer patients, we investigated whether hypoxia in human PrECs, prostate cancer and myeloid cell lines promotes NLRP3 and AIM2 inflammasome activation." (PMID 27058421, 2016). "Notably, sensing of the cytosolic DNA (synthetic DNA poly [dA:dT]), by “primed” PrECs and prostate cancer cell line PC-3 also activated the AIM2 inflammasome activity." (PMID 27058421, 2016). "A recent study has shown that the AIM2 inflammasome plays a critical role in both human prostatic diseases, such as benign prostate hyperplasia (BPH) and prostate cancer." (PMID 40002808, 2025). "AIM2 is an interferon (IFN) inducible protein, which is constitutively downregulated in prostate cancer." (PMID 27429614, 2016). "AIM2 was originally considered as a tumor suppressor gene that is frequently repressing in a variety types of tumors, including renal carcinoma, prostate cancer, and hereditary nonpolyposis colorectal cancer (HNPCC)-associated small bowel cancer." (PMID 33842454, 2021). "AIM2, an interferon (IFN) inducible protein, is constitutively down-regulated in prostate cancer, however, IFN-induced AIM2 inflammasome activation leads to increased production of IL-1β and IL-18 in prostate cancer cell lines." (PMID 30631327, 2018). "We found that the mRNA level was very much variable across the cell lines, and there was no consensus on the expression levels of NLRP3, NLRC4, NLRP6, and AIM2 among early stage (e.g. LNCaP and LNCaP-Ln3) and late stage (e.g. PC3 and DU145) prostate cancer cell lines." (PMID 28663562, 2017).
renal carcinoma (15 papers, 2018 to 2025). A carcinoma arising from the epithelium of the renal parenchyma or the renal pelvis. "In renal carcinoma models, AIM2 enhances the polarization switch of tumor-associated macrophages (TAMs) from the anti-inflammatory M2 phenotype to the pro-inflammatory M1 phenotype." (PMID 39076969, 2024). "We observed AIM2 overexpression in 8 cancers and its association with poor prognosis in two kidney carcinomas (KIRC and KIRP)." (PMID 32328125, 2020). "This virus significantly inhibited tumor cell proliferation and promoted apoptosis and cell killing by efficiently expressing E1A and AIM2 in renal carcinoma cells, further confirming the antitumor activity of AIM2 in RCC." (PMID 39450183, 2024). "In renal carcinoma patients, low AIM2 expression is correlated with lymph node metastasis, poor 5-year overall survival, and poor disease-specific survival." (PMID 36932407, 2023). "TAM-derived AIM2 inflammasomes in renal carcinoma also show a protective role in tumor invasion and metastasis through a different mechanism." (PMID 36932407, 2023). "In renal cancer, AIM2 can induce the transformation of anti-inflammatory M2 to pro-inflammatory M1 by enhancing the inflammasome pathway, thus inhibiting tumor progression." (PMID 35281845, 2022). "We also examined the role of Ad‐CAIXpromotor‐AIM2 on the migration of renal cancer cells through the transwell assays." (PMID 32725966, 2020). "Ad‐CAIXpromotor‐AIM2 decreased cell viability, and induced cell apoptosis and cell killing in human renal cancer cells." (PMID 32725966, 2020). "In the present study, we constructed CAIXpromotor controlled oncolytic adenovirus expressing AIM2 (Ad‐CAIXpromotor‐AIM2) and evaluated its efficacy and toxicity in renal cancer cells or tumour models." (PMID 32725966, 2020). "In this study, we explored that the therapeutic gene AIM2 enhanced the anti‐tumour effect of CAIXpromotor by regulating Ad tumour‐specific replication in renal cancer." (PMID 32725966, 2020). "Ad‐CAIXpromotor‐AIM2 demonstrates its tumour cell‐specific replication by efficiently expressing E1A and AIM2 in renal carcinoma cells." (PMID 32725966, 2020). "The inhibition ability of cell migration by Ad‐CAIXpromotor‐AIM2 in renal cancer cells was blocked by the YVAD‐CMK inhibitor." (PMID 32725966, 2020). "CCK‐8 assays demonstrated that Ad‐CAIXpromotor‐AIM2 remarkably reduced the proliferation of renal carcinoma cells at time‐dependent, and this reduced proliferation was stronger on OSRC‐2 cells than that in 786‐O cells." (PMID 32725966, 2020). "Effect of Ad‐CAIXpromotor‐AIM2 on cell proliferation in renal cancer cells was assessed by the colony formation assay in vitro." (PMID 32725966, 2020). "The result showed AIM2 expression was significantly increased in both renal cancer cell lines as compared with control." (PMID 30160343, 2018). "The effect of AIM2 on the migration of renal cancer cells was further examined by wound healing assay." (PMID 30160343, 2018). "Similarly, AIM2 has also been reported to favor M1 polarization while suppressing M2 markers in renal carcinoma." (PMID 40490723, 2025). "AIM2 activation in macrophages also contributes to kidney injury, and renal carcinoma." (PMID 39076969, 2024). "The distinct metabolic profile of renal cancer is intimately associated with its sensitivity to ferroptosis, with multiple molecular mechanisms implicated in the regulation of ferroptosis in renal cancer, including PDIA4, GPX4, KLF2, ACSL3, and AIM2." (PMID 39092291, 2024). "A bioinformatics analysis that establishes a risk-scoring system involving inflammasomes indicates higher AIM2 expression may relate to poorer overall survival in renal carcinoma patients." (PMID 36932407, 2023). "Likewise, AIM2 enhances the induction of autophagy and inhibits the migration and invasion of renal carcinoma cells." (PMID 34740380, 2021).